IL2 (interleukin 2)
Diseases named in the same sentence as IL2 in open-access papers (continued):
Sharing a sentence is not in itself a finding about the gene and the disease.
tumor (continued). "Our results suggest that IL-2 and TNF-α should be evaluated in a larger study to better understand their role in pathogenesis and prognosis, as they showed a significant relationship or a trend of relationship with tumor stage and PR." (PMID 40869161, 2025). "Increased IL-2 secretion directly upregulates MHC-I expression, enhances immune cell infiltration and T cell activation, increases the immunogenicity of PTC cells, and overcomes immune evasion, thereby limiting tumor progression." (PMID 40230479, 2025). "The foundational role of IL-2 in supporting adoptively transferred TILs was demonstrated in early NSCLC studies, where TILs could be successfully expanded from minimally invasive tumor biopsies." (PMID 40904467, 2025). "After infusion, IL-2 promotes TIL survival via signal transducer and activator of transcription-5 (STAT5) signaling, while chemokine receptors like C-X-C chemokine receptor 3 (CXCR3) and C-C chemokine receptor 5 (CCR5) guide TIL migration to tumor sites." (PMID 40904467, 2025). "Immunofluorescence (IF) analysis revealed that Neo-2/15 rather than IL-2 profoundly improved the persistence of BBζ in tumor tissues especially at 72 hours after intratumoral injection." (PMID 40025022, 2025). "The cytokines IL-2 and TNF-α showed a significant correlation with tumor stage." (PMID 40869161, 2025). "In tumor therapy, the enhanced permeability and retention (EPR) effect allows nanoparticles to passively accumulate more efficiently in tumor tissues, making them ideal carriers for delivering proinflammatory cytokines such as IL-2, IL-12, and TNFα." (PMID 40557148, 2025). "Except for IL-2, GM-CSF, IL-6, and IL-18 showed a negative correlation with tumor growth in CRT-NP treated patients." (PMID 40386779, 2025). "The resulting IL-2 levels are sufficient to expand tumor-specific T cells without inducing the generation of immunosuppressive Treg cells." (PMID 41374974, 2025). "Interestingly, at low E:T ratios (2.4:1), expanded MVCAR exhibited significant upregulation of human IL-2 and human IFN-γ cytokine secretions accompanied by significantly enhanced anti-tumor cytotoxicity as compared with monovalent CAR T cells." (PMID 40896578, 2025). "L19–IL-2 is another widely studied WT IL-2 immunocytokine, consisting of a non-covalent homodimeric scFv format with improved tumor-homing properties and penetration into the TME." (PMID 41568361, 2025). "Additionally, there was an increase in activated cytotoxic T cells (CTLs), including CD8+/IFN‐γ+, CD8+/IL‐2+, and CD8+/IL‐2+/IFN‐γ+ cells, in the spleen and tumour‐draining lymph nodes." (PMID 40830825, 2025). "Counts of IL-7–ALT CD8+ T cells in tumor were also increased compared with IL-2 ALT throughout, though differences were nonsignificant." (PMID 40244705, 2025). "Ex vivo stimulation of PBMCs with tumor lysate or peptide pools performed approximately 4–6 weeks after ablation (relative to Day 0) can quantify the frequency and polyfunctionality (production of IFN-γ, TNF-α, IL-2) of tumor-reactive T cells." (PMID 41295487, 2025). "During the process of in vitro expansion and repetitive stimulation, along with the high concentrations of inhibitory cytokines in the tumor microenvironment, CAR-T cells develop an exhausted phenotype (upregulation of PD-1, LAG3, TIM3, and TIGIT and decreased secretion of IL-2, TNF-α, and IFN-γ)." (PMID 40002679, 2025). "Furthermore, we assessed the level of secreted cytokines, including IFN-γ, TNF-a, IL-2, and IL-10, produced from the co-culture of CAR-T cells with tumor cells at an effector-to-target (E:T) ratio of 16:1." (PMID 40722671, 2025). "SPs extracted from G. lemaneiformis and G. fisheri have demonstrated potent anti-tumour activities by inducing apoptosis through various mechanisms, including the upregulation of CD8+ T cells and IL-2, inhibition of EGFR/MAPK/ERK signalling pathways, and activation of the Fas/FasL pathway." (PMID 40077614, 2025).
tumor (continued). "A further issue is the limited expansion of CAR-NK cells in vivo after transplantation, due to tumour heterogeneity and a lack of cytokines, e.g., IL2 and IL15." (PMID 40650066, 2025). "EcN exhibits inherent tumor-colonizing capabilities and has effectively been utilized to administer tumor-specific neoantigens (e.g., CT26-derived MHCIa, MHCIIa, MHCI/IIv), therapeutic cytokines (IL-2), and nanobodies, all of which elicit robust systemic immune responses." (PMID 40282924, 2025). "Their activity against tumor-specific antigens was then determined with tetrazolium (MTT), chromium-51 (51Cr) release, or cell counting kit 8 (CCK8) assays, or by measuring cytokine levels (IFN-γ, TNFα, IL-2) with ELISA." (PMID 40700119, 2025). "Administration of either IL-2/S4B6 or IL-2/JES6 (2 μg IL-2/dose) before ICIs did not affect tumor growth compared with ICIs alone and led to slightly worse (though not statistically significantly) survival." (PMID 40789741, 2025). "The lack of an improved anti-tumor response through the IL-2 combination in vivo prompted us to investigate other combination treatment partners." (PMID 40063100, 2025). "As tumor stage advanced, IL-2 expression appeared to fluctuate in a non-linear fashion, demonstrating a pattern consistent with increasing tumor severity." (PMID 40869161, 2025). "Furthermore, bempegaldesleukin (NKTR-214, an immunostimulatory IL-2 prodrug), which is competent in activating and continuously expanding CD4+ T and CD8+ T cells, manifests a synergistic anti-tumor effect when combined with ICIs." (PMID 40191187, 2025). "Effector T cells, primarily CD8+ cytotoxic T lymphocytes (CTLs) and CD4+ helper T cells, are critical for directly targeting and eliminating tumor cells through the release of cytokines such as IFN-γ, TNF-α, and IL-2, and the use of cytotoxic granules containing perforin and granzymes." (PMID 40475782, 2025). "Various immune-activating cytokines and chemokines (i.e. CXCL11, CCL2/5/19, FLTL3, IFN-α/β/γ, IL2/7/12/15/18/23/24, TNF-α, etc.)are being investigated on preclinical tumor models (neuroblastoma, breast tumor, lymphoma, lung cancer, glioma, melanoma, etc.)and in clinical trials." (PMID 40697381, 2025). "Clinical trials have reported sizable tumor regression (30%–63%) in 5 out of 25 patients with 10 different cancer diagnoses treated with TILs and low-dose IL-2 (200,000 IU/kg for 14 days), with no severe IL-2-related adverse effects reported." (PMID 40458394, 2025). "SE modulated IL-2, IL-4, IL-6, IL-17, IFN-γ, and TNF-α in tumor environment." (PMID 40807278, 2025). "Elevated B7H3 could decreased the secretion of IFN-γ, IL-2, TNF-α, and IL-13, which is important for activation and proliferation of tumor-infiltrating lymphocytes (TILs)." (PMID 41291854, 2025). "Additionally, IL-2 and IFN-γ were also quantified, being involved in the NK-mediated anti-tumor response." (PMID 41465318, 2025). "Taken together, the combination of VACV-mediated tumor therapy with CTL epitopes and IL2 may be a very promising, novel choice for enhancing the cytotoxic T cell response against tumors." (PMID 41050655, 2025). "Moreover, CAR-M would secrete IL-1, IL-2, and IL-15, which would upregulate CAR-NK cells and enhance their cytotoxicity against tumour cells." (PMID 40650066, 2025). "However, considering its importance in immunotherapy, novel mutants of IL-2, such as FSD13, were designed to handle the side effects to a large extent and showcased improved anti-tumor effects with limited toxicity." (PMID 40670434, 2025). "Additionally, activated CAR-T cells release cytokines including IL-2, IL-6, and IFN-γ, which attract and activate immune cells like macrophages, natural killer (NK) cells, and more T cells, thus promoting tumor suppression." (PMID 40584631, 2025).
tumor (continued). "Hence, this study chose to assess serum concentrations of TNF‐α, IL‐2, IL‐10, MMP‐9, and VEGF‐C to reflect the conditions of the tumor microenvironment before metastasis." (PMID 40808216, 2025). "We sought to engineer molecules that could reverse immunosuppression in the context of cancer, for example, by inhibiting tumor-derived TGF-β and stimulating the IL-2 pathway." (PMID 40069219, 2025). "In the tumor microenvironment, overexpressed PD-L1 is capable of interacting with PD-1 on sensitized immune cells, inducing T cell proliferation suppression and the production of cytokines, such as interferon-γ (IFN-γ) and interleukin 2 (IL-2)." (PMID 40333811, 2025). "Prior to TILs reinfusion, patients undergo preparatory regimens, including non-myeloablative (NMA) lymphodepletion and interleukin-2 (IL-2) administration, to prime the tumor microenvironment for optimal antitumor activity of reinfused TILs." (PMID 40458394, 2025). "Furthermore, engineered IL-2 partial agonists have been shown to preserve the stem-like properties and mitochondrial fitness of CD8+ T cells, thereby enhancing anti-tumor immunity." (PMID 41268548, 2025). "CIK cells, primarily consisting of CD3+CD56+ T-cell subsets generated by stimulation with IFN-γ, IL-2, and anti-CD3 monoclonal antibodies, mediate tumor cell killing through both the perforin/granzyme B pathway and death receptor-mediated signaling such as Fas/FasL." (PMID 40904467, 2025). "This demonstrates that the combined treatment of Palbociclib and IL-2 works together to activate CD8+ T cells with a stronger immune response, suggesting that such a combination strategy can produce better immune responses and anti-tumor effects." (PMID 38352877, 2024). "Furthermore, BTLA + CD4 + T-cells produced less IL-2 compared to those from healthy mice, while BTLA + CD8 + T-cells in tumor- bearing mice had impaired IL-2 and TNF production." (PMID 38233898, 2024). "In a follow-up study the same authors showed that the IL-2/CD25 fusion protein also induces anti-tumor immune response in the absence of a vaccine and outperforms an IL-2Rβγc biased IL-2v (IL-2/anti-IL-2 S4B6 complexes)." (PMID 39114660, 2024). "Other studies have reported models focusing on one or on parallel pathways of inhibitory factors induced by Treg, TGF-β and/or IL-10 that promote tumor growth and reduce the cytotoxicity of effector cells (i.e., CD8+ cells and others such as DC, CD4+ helper T cells, and IL-2)." (PMID 39598584, 2024). "Subsequently, they assist the anti-tumor process by recruiting CD8+ T cells, promoting their proliferation and enhancing T cell effector function through the production of IFN-γ-dependent chemokines and IL-2." (PMID 38792234, 2024). "The blood levels of cytokines such as IL-2 (P = 0.0391) and CXCL10 (P = 0.0195) were also significantly increased in the pCR group, which is consistent with the high density of activated cytotoxic T cells at the tumor site (P < 0.0001)." (PMID 38619623, 2024). "Moreover, miR-28 and miR-138 can target immune checkpoints and revert exhausted phenotypes, with miR-28 specifically resulting in interleukin-2 (IL-2) and tumor necrosis factor-alpha (TNF-α) secretion in the tumor microenvironment." (PMID 39329777, 2024). "However, CD4+ regulatory T cells can suppress immune function, leading to IL-2 depletion, reducing CD8+ T cell infiltration and activity in tumor tissues, thus facilitating tumor cell immune escape." (PMID 38312647, 2024). "Given the in vitro synergistic anti-tumor function of IRF1 and IL-2, we further explore the potential immune cell types which might play a major role in the complex tumor microenvironment." (PMID 38915471, 2024).
tumor (continued). "Meanwhile, the effector cytokines tumor necrosis factor (TNF)‐α, interferon (IFN)‐γ, and interleukin (IL)‐2, secreted by both original CAR‐T cells and CAR‐ap‐enriched CAR‐T cells, could be significantly elevated when co‐incubated with tumor cells." (PMID 38148412, 2024). "Conversely, strong negative correlations with tumor burden were found with IL-2 (r=-0.6589, p = 0.0275) and IL-9 (r=-0.7606, p = 0.0066)." (PMID 39623404, 2024). "Compared with the PBS-treated group, the Palbociclib-treated group had a TSR of 35.29%, whereas the IL-2 group did not exhibit a significant anti-tumor effect." (PMID 38352877, 2024). "An important consideration in these trials is the fact that ZOL + IL‐2 treatment is known to induce proliferation of NK cells, hence an anti‐tumour effect from these cells cannot be completely ruled out." (PMID 38375329, 2024). "In addition, the VGRmIL2-IC enhances the anti-tumor cytotoxic effect while conserving the proliferative and IFN-γ induction properties of IL-2." (PMID 38337114, 2024). "The increase in IL-2 and CXCL10 might reflect the chemotaxis and enrichment of cytotoxic T cells at the tumor site and a better response to neoadjuvant chemoimmunotherapy." (PMID 38619623, 2024). "However, when HER2-CAR-T cells and PD-1 blockade were combined, more interleukin-2 (IL-2) and interferon-gamma (IFN-γ) were released, which led to greater tumor elimination." (PMID 38486856, 2024). "Moreover, we further validated the results from previous studies by knocking out PD-L1 in tumor cells, PD1CD28 chimeric molecule expression enhanced IL-2 secretion and T cells proliferation in a PD-L1-dependent manner." (PMID 39352918, 2024). "We harnessed its impact on the tumor immune microenvironment and combined it with IL-2 to counteract IL-2’s immunosuppressive effect, aiming to enhance the immune response and improve the anti-tumor effect without increased toxicity." (PMID 38352877, 2024). "Chemotherapy drugs can enhance the recognition and presentation of dendritic cells (DCs), activate cytotoxic T lymphocytes to attack tumors, stimulate the release of interleukin-2 (IL-2), IL-4, and interferon-gamma (IFN-γ), and induce anti-tumor immune responses." (PMID 38809459, 2024). "Nevertheless, the association between the upregulation of cytokines TGF-β, IL-4/IL-13, IL-10, IL-6, and IL-2 and the overexpression of FAP across multiple tumor types highlights a crucial link between FAP+ CAFs, tumor progression, and evasion of immune surveillance." (PMID 39035007, 2024). "IL‐2 is secreted by activated T cells in the body, by inducing T cell proliferation differentiation, enhancing cell toxicity of CTL, and promoting NK cells and LAK cells to kill tumor cells." (PMID 39003635, 2024). "Notably, cytokines like IL-2, IL-6, TNF-α, and IFN-γ, known for their inflammatory enhancement properties, contribute to stimulating tumor cell immunity, thereby fostering anti-tumor activity." (PMID 39351237, 2024). "According to a report, primary melanoma tumors that spontaneously regress (a clinically confirmed event suggesting host anti-tumor immune response activation) express significantly more TH1-linked genes, such as IL-2 and TNFβ, than tumors that do not." (PMID 39712007, 2024). "Nevertheless, IL-13 does not act as a growth factor but inhibits IL-2-induced tumor cell proliferation and spontaneous apoptosis of cells in tumor masses." (PMID 39057050, 2024). "Furthermore, we demonstrated that stimulating the IL-2 and CD95 pathways with low cytokine and agonist antibody doses can induce tumour proliferation." (PMID 39766250, 2024). "Vaccine specific T cells in IL-2/CD25 fusion protein treated mice expressed higher levels of Granzyme B as well as IFN-γ, showed a less exhausted phenotype and facilitated an improved anti-tumor immune response." (PMID 39114660, 2024).
tumor (continued). "Treatment with the combination of WT IL-2 and either T3-HDVax or Irr-HDVax did not induce tumour rejection but resulted in significant toxicity, evidenced by weight loss in treated mice." (PMID 39048822, 2024). "There have also been developed cell-free tumour vaccines containing α-fetoprotein-enriched DC-derived exosomes, which stimulate immune cells to produce IFN-γ and IL-2 and reduce the expression of TGFβ and IL-10 at the site of the tumour, thus, inducing antigen-specific response to cancer cells." (PMID 38200509, 2024). "We observed that GSDME could increase the infiltrations of CD8+T cells and their functions secreting more IL2, TNFα, GZMB, and PFN against tumor in human samples." (PMID 38853246, 2024). "Additionally, multiple studies have shown that combining CEA-CAR T cell therapy with cytokines, such as recombinant IL2 and IL12, can further enhance anti-tumor effects." (PMID 39397869, 2024). "In stark contrast, OT1 cells undergoing LSD1 depletion during the IL-2 expansion phase post-TCR stimulation (4-OHT treatment during day 2–4) did not impact tumor growth, similar to cells retaining LSD1 function (no 4-OHT treatment)." (PMID 38773088, 2024). "In our study, we observed a significant increase in IFN-γ and IL-2 levels in mice following L.p CMU-Pb-L5 intervention, suggesting that L.p CMU-Pb-L5 may regulate the expression of anti-tumor immune-related cytokines to inhibit tumor growth." (PMID 39439459, 2024). "Thus, targeting an IL-2 mutein to CD8+ T cells circumvents HDVax inhibition by increasing the frequency of antigen-specific cytotoxic CD8+ T cells, leading to tumour regression." (PMID 39048822, 2024). "Moreover, gp96 deletion impeded Treg activation primarily by suppressing IL-2/STAT5 signaling, which also contributed to tumor regression." (PMID 38787791, 2024). "IL-15 administration, like IL-2, has been shown to stimulate NK cell cytotoxicity and promote anti-tumor responses, though with less toxicity and absence of Treg stimulation, which present challenges to IL-2-based therapies." (PMID 38545115, 2024). "Without IL-2 administration, tumor regrowth occurred after 18 days post-treatment with CAR-NK cells, emphasizing the need for repeated IL-2 injections to enhance NK cell longevity and anticancer activity." (PMID 38694508, 2024). "Similarly, in KIRP SIGLEC12 positive tumours, a weak positive correlation in PDCD1 (Fig. 4C1), CD274 (Fig. 6C2), CTLA4 (Fig. 6C3), IL-2 (Fig. 6C4) was observed." (PMID 38268823, 2024). "Tumor tissues from 12 patients undergoing surgery for primary CRC surgery were cut for pathological examination and transferred to a one-time perfusion bioreactor with a starting medium containing IL-2 and IL-12." (PMID 39238638, 2024). "The ability of anti-LILRB4 to restore IL-2 production in HDVax-induced CD4+ T cells prompted us to ask whether IL-2 supplementation would restore effector CD8+ T cell function and tumour rejection." (PMID 39048822, 2024). "Moreover, interleukins like IL-2 interact with TGF-β in immune signaling; IL-2, along with TGF-β produced by tumor cells, promotes the generation of regulatory T cells (Treg), which generally counteract anti-tumor immunity." (PMID 38900304, 2024). "In summary, targeting IL-2 to well characterized tumor antigens recapitulated IL-2 mediated anti-tumor efficacy but largely failed to avoid serious treatment related toxicities." (PMID 39114660, 2024). "Subsequently, to test whether YTHDF1 regulated the immunosuppressive tumor microenvironment, the immunosuppressive cytokines (IL-10, TGF-β) and immune effector cytokines (IFN-γ, IL-2) were tested." (PMID 39557826, 2024). "An area that has not been considered widely in the engineering of IL-2 is the impact of the physicochemical properties of the tumor microenvironment on the activity of IL-2." (PMID 39114660, 2024).